LCN2 (lipocalin 2)
Diseases named in the same sentence as LCN2 in open-access papers (continued):
Sharing a sentence is not in itself a finding about the gene and the disease.
Obesity (continued). "The lipocalin family proteins, including lipocalin-2 and retinol-binding protein 4 (RBP4), are adipokines closely associated with obesity-related metabolic disorders." (PMID 23799122, 2013). "LCN2 is a 25 kDa glycoprotein that is secreted abundantly by adipose tissues, and hence elevated in conditions of obesity." (PMID 23119072, 2012). "Lipocalin-2 has been reported to be elevated in certain metabolic disorders, including obesity, polycystic ovary syndrome and type 2 diabetes." (PMID 22292925, 2012). "Among these, the lipocalin family proteins, FABP4, LCN2 and RBP4, have been identified as adipokines associated with obesity, type 2 diabetes and metabolic syndrome." (PMID 23119072, 2012). "We measured serum leptin, adiponectin, serum amyloid A, keratinocyte-derived chemokine, and lipocalin-2 concentrations because these have a role in insulin resistance, type-2 diabetes, and obesity." (PMID 21314942, 2011). "Leptin reduced the elevated gene expression of tissue-type plasminogen activator (Plat) and lipocalin-2 (Lcn2), which are upregulated in many inflammatory conditions, including human obesity." (PMID 20671928, 2010). "Furthermore, lipocalin 2, another adipokine upregulated in obesity, is a marker of pancreatic cancer and, when depleted in a mouse model, reduces pancreatic cell growth." (PMID 40129249, 2025). "Additionally, it has been reported that LCN2 inhibition protects against the development of hyperglycemia and insulin resistance in obesity." (PMID 39808380, 2025). "Although lipocalin-2, pentraxin-3, and osteoprotegerin are generally considered pro-inflammatory or obesity-related, their elevation in the FIP + Fat group may reflect regulatory or tissue-protective roles in certain settings." (PMID 40998975, 2025). "It is hypothesized that under “normal” physiological conditions LCN2 is predominantly produced by bone, whereas in pathological states such as obesity and type 2 diabetes, production from adipose tissue is increased." (PMID 39830147, 2025). "Previous research has indicated that an acute increase in LCN2 may be the result of a protective mechanism in obesity-related metabolic dysfunction to suppress appetite and protect β-cell function in the early stages of disease." (PMID 39830147, 2025). "Moreover, greater production of LCN2 in obesity has been observed by transcriptional regulation of the Lcn2 gene, NF-kappaB and CCAAT/enhancer-binding protein (C/EBP) pathways." (PMID 38308309, 2024). "There are two studies that report that LCN2 is not affected by PCOS, but that obesity in patients with PCOS is associated with alterations of serum LCN2 levels." (PMID 38645429, 2024). "Taken together these findings suggest that the increased levels of LCN2 may exert protective role in obesity." (PMID 38035773, 2024). "However, the precise roles of LCN2 in diabetes, obesity, and muscle dysfunction still need to be elucidated in depth." (PMID 37326909, 2024). "In obesity, LCN2 promotes the development of insulin resistance and T2D." (PMID 38201988, 2024). "Obesity affects not only LCN2 expression in adipocytes, but also in the reproductive tract." (PMID 38645429, 2024). "Besides RBP4, lipocalin-2 (LCN-2) is another protein that belongs to the lipocalin family which also plays a significant role in obesity-related diseases." (PMID 39139157, 2024). "Numerous studies showed elevated lipocalin-2 levels in patients with obesity." (PMID 37025415, 2023). "Increased lipocalin-2 levels (p = 0.033) could be observed between individuals with obesity (n = 18) compared to lean individuals (n = 15)." (PMID 37025415, 2023). "Lean individuals had lower lipocalin-2 levels compared to patients with obesity (p = 0.033)." (PMID 37025415, 2023). "We hypothesized significantly different lipocalin-2 levels existed in individuals with low BMI (healthy lean individuals and females with AN) and patients with obesity." (PMID 37025415, 2023).
Obesity (continued). "Therefore, it is necessary to elucidate the role of lipocalin-2 in obesity and its systemic effects on bones to establish robust conclusions." (PMID 36831188, 2023). "They postulated that LCN2 may influence the progression of insulin resistance in gestational diabetes and its expression in adipose tissue can be correlated with obesity in women with GDM." (PMID 38203346, 2023). "The protein Lcn2 is related to insulin resistance, obesity, and atherosclerotic diseases." (PMID 36983014, 2023). "As in adipocytes, LCN2 expression and secretion is also induced by LPS treatment in macrophages, indicating that macrophages are another important source of LCN2 production in AT during obesity (Guo, Jin, and Chen 2014)." (PMID 35909571, 2022). "LCN2 expression was then investigated in obesity related metabolic disorders." (PMID 35034646, 2022). "Given the anti-inflammatory role of LCN2, elevated circulating LCN2 levels could be a protective mechanism against obesity-induced inflammation." (PMID 35909571, 2022). "Additionally, LCN2 expression in the AT is also significantly increased in animal models of obesity and diabetes and in insulin resistant and diabetic subjects." (PMID 35406450, 2022). "Current research using both animal and human participants suggests that obesity may increase heart size, which is partially mediated by an increase of lipocalin-2 expression and thus leads to heart failures and various other cardiovascular complications." (PMID 36012601, 2022). "Moreover, LCN2 deletion improved insulin sensitivity in adipose tissue of diet-induced obesity or attenuated non-alcoholic steatohepatitis (NASH) progression in the liver of methionine- and choline-deficient-diet mice." (PMID 36501079, 2022). "Our previous observations indicated that patients with obesity had elevated serum LCN2 levels." (PMID 35138515, 2022). "Moreover, a very recent study revealed that bones are the primary contributor to increased circulating LCN2 levels in HFD-induced obesity models is mainly contributed by bone, as this increase is lost following the deletion of LCN2 in osteoblasts." (PMID 35909571, 2022). "LCN2 may act as an anti-obesity agent by upregulating thermogenic markers, leading to browning in white adipose tissue." (PMID 35725366, 2022). "Elevated serum LCN2 levels have been found in obesity models in mice and humans." (PMID 35138515, 2022). "Our study suggests that elevated serum LCN2 levels in patients with obesity might serve as a biomarker or even play an important role in weight reduction after LSG surgery." (PMID 35138515, 2022). "Plasma LCN2 levels, however, may be attenuated over longer time periods as participants recover from obesity and concomitant chronic low-grade inflammation." (PMID 33603000, 2021). "Elevated LCN2 levels are typically found in obese humans and mouse models of obesity." (PMID 34680216, 2021). "However, because LCN2 is modified by age, sex, obesity, and numerous metabolic variables, the results of serum or cerebrospinal fluid (CSF) LCN2 are ambiguous for memory impairment." (PMID 34829528, 2021). "And our data revealed that the elevated LCN2 expression in obesity might be a potential protective factor against gastric injury by repressing endoplasmic reticulum stress-mediated apoptosis." (PMID 33637683, 2021). "In both obesity-induced and acute gastric injury, we found gastric mucosa apoptosis level was increased and LCN2 might suppress this process." (PMID 33637683, 2021). "Furthermore, LCN2 protects against obesity and metabolic syndrome by interfering with the composition of gut microbiota." (PMID 34884961, 2021). "Taken together, it is conceivable that elevated LCN2 during obesity is a driver of PDAC development and progression, although further studies are clearly needed to cement that hypothesis." (PMID 34680216, 2021). "As reported by former studies, LCN2 is considered as an obesity-related hormone." (PMID 33637683, 2021).
Obesity (continued). "This feedback loop indicates that the induced LCN2 expression may act as a protective factor in obesity." (PMID 33637683, 2021). "The researchers suggested that LCN2 could act in the development of insulin resistance in GDM, and its expression in subcutaneous adipose tissue may be associated with obesity in GDM women." (PMID 34212049, 2021). "Increased LCN2 may act as a protective factor in obesity-induced gastric injury by inhibiting endoplasmic reticulum stress-mediated apoptosis." (PMID 33637683, 2021). "By contrast, non-polyaminated LCN2 [represented by C87A in the present study] accumulates in tissues to cause injury and is implicated in the pathogenesis of obesity-associated cardiovascular complications." (PMID 34938273, 2021). "In fact, Yan et al160 found that LCN2 expression in adipocytes leads to insulin resistance in adipocytes, and that LCN2 could control insulin sensitivity in patients with obesity." (PMID 33945675, 2021). "Our recent studies demonstrated that Lcn2 deficiency reshapes gut microbiota and remodels the microbiota-derived metabolome, including decreased production of short-chain fatty acids (SCFAs) and SCFA-producing microbes during diet-induced obesity." (PMID 34572499, 2021). "Given that obesity can accelerate the progression of skeletal muscle atrophy in the elderly, we sought to determine whether upregulation of LCN2 expression in sarcopenic muscles induces inflammation and oxidative stress in obese ob/ob mice." (PMID 34064680, 2021). "NGAL, also known as lipocalin-2, is one of the lipocalins transporting small and hydrophobic molecules including fatty acids and hormones, and its expression is upregulated in various conditions including infection, diabetes, obesity, and cancer." (PMID 34884709, 2021). "Given the role of the MMP system in adipocyte differentiation and SAT and VAT remodelling, this may implicate Lcn2 in the development of obesity." (PMID 33528828, 2021). "By treatment of cells with LCN2 recombinant protein or siRNA, we revealed that the elevated LCN2 expression in gastric mucosa in obesity may also be protective." (PMID 33637683, 2021). "Failure to stimulate postprandial LCN2 in individuals with obesity may contribute to metabolic dysregulation, suggesting that LCN2 may be a novel target for obesity treatment." (PMID 33231171, 2020). "Although Lcn2 is known to be upregulated during various inflammatory conditions, its biological activity during the progression of chronic inflammatory metabolic disorders such as obesity is still controversial." (PMID 32883997, 2020). "The experiments lay the initial groundwork for testing whether LCN2 might be a useful treatment for obesity." (PMID 33231171, 2020). "Recent studies have shown that Lcn2 is secreted by adipocytes in response to inflammation and is categorized as a new adipokine cross-linking innate immunity and metabolic disorders including obesity." (PMID 32883997, 2020). "While we hypothesize that exogenous administration of rec-Lcn2 may have anti-obesity effects in the Lcn2KO mice, the significance of increased systemic Lcn2 levels with age in the context of obesity is not clearly understood." (PMID 32883997, 2020). "Transcriptional activation of LCN2 gene in adipose tissue has been hypothesized to be related to inflammation and obesity." (PMID 33192583, 2020). "Even though more thorough pharmacological studies are warranted in the future, this set of data suggests that LCN2 could be developed into an effective and safe treatment for obesity." (PMID 33231171, 2020). "Taken together, both in vitro and in vivo studies suggest that Lcn2 is a naturally occurring adipokine, and may serve as an anti-obesity agent by upregulating the thermogenic markers resulting in the browning of WAT." (PMID 32883997, 2020). "Nonetheless, exogenous supplementation of Lcn2 may confer protection against ongoing obesity and inflammation." (PMID 32883997, 2020).
Obesity (continued). "Together, these results indicate that LCN2 deficiency did not increase food consumption or degree of obesity during high fat diet-feeding." (PMID 31488870, 2019). "Serum levels of LCN2 correlate with obesity and BMI, especially in severely obese women." (PMID 31208019, 2019). "To test this hypothesis, we induced obesity in Lcn2+/+ and Lcn2−/− mice by HFD-feeding for 20 weeks, and then treated each group with vehicle or celastrol (100 μg/kg, i.p., once a day) for three weeks." (PMID 31488870, 2019). "Considering our own results that celastrol increases bone marrow and plasma LCN2, we hypothesized that LCN2 might mediate the anti-obesity effects of celastrol." (PMID 31488870, 2019). "However, LCN2 has been shown to have contradictory roles in the development of obesity or diabetes in rodents." (PMID 30761088, 2019). "As a member of the lipocalin gene family, LCN2 influences obesity and diabetes in humans." (PMID 31665138, 2019). "LCN2 was previously suggested as an anorexigenic and anti-obesity agent." (PMID 31488870, 2019). "Importantly, a number of lipocalins, most notably lipocalin-2 (LCN2) and RBP4 have been associated with adipose tissue expression and obesity." (PMID 29760587, 2018). "LCN2-null male mice are protected from high fat diet-induced obesity and insulin resistance." (PMID 29736189, 2018). "There is very limited information about LCN15 in the literature, and its physiological function is unknown; however, it is a member of the lipocalin gene family, of which LCN2 is a well-studied member involved in obesity and diabetes." (PMID 29736189, 2018). "Findings so far show that Lcn2 KO mice were resistant against diet-induced obesity, and BAT activity might be more enhanced in KO than WT mice after HFD." (PMID 29138470, 2017). "Therefore, it was suggested that the estrogen receptor is a transcriptional regulator of LCN2 that promotes tumorigenesis in the context of obesity." (PMID 29234288, 2017). "Obesity, determined by BMI, was insignificantly correlated with LCN2 in this study." (PMID 28709459, 2017). "LCN2 regulates lipid and energy metabolism in obesity and is upregulated in response to insulin." (PMID 29234288, 2017). "A significant negative correlation was observed between Lcn2 expression and gut Rumincoccus abundance, in keeping with the negative association of this bacterial species with the obesity parameters." (PMID 27845741, 2016). "Lipocalin-2 seems to act as a dual molecule with regard to inflammation in obesity." (PMID 26263971, 2015). "Circulating levels of lipocalin-2 were increased in adults with obesity and MetS." (PMID 25356508, 2014). "LCN2 is an early biomarker of liver damage and inflammation related to obesity." (PMID 24871103, 2014). "As shown in our previous studies, Lcn2 expression is increased in adipose tissue in obesity." (PMID 24818605, 2014). "Also in psoriasis, LCN2 has been investigated in metabolic syndrome, atherosclerosis, obesity, and diabetes mellitus." (PMID 24803721, 2014). "Lipocalin-2 is elevated in animal models of obesity and in obese humans." (PMID 24205333, 2013). "Lipocalin-2 is elevated in obesity, diabetes and non-alcoholic fatty liver disease." (PMID 24205333, 2013). "Expression of Lcn-2 in adipose tissue is elevated in various experimental models of obesity and in obese humans, suggesting that Lcn-2 may participate in inflammation-related disorders." (PMID 22957064, 2012). "Thus, further prospective large population-based studies are needed to investigate the role of lipocalin-2 in obesity--induced insulin resistance." (PMID 22292925, 2012). "Furthermore, due to LCN-2 high expression in serum or urine in inflammatory systemic diseases, such as kidney disease, rheumatic diseases, obesity, diabetes, and heart failure, has been proposed as a potential biomarker linking periodontitis and systemic diseases." (PMID 39516276, 2025).
Obesity (continued). "A recent study has also suggested that circulating LCN2 may be protective against obesity and T2DM." (PMID 39411310, 2024). "LCN2, known as neutrophil gelatinase-associated lipocalin (NGAL), is an antimicrobial protein and multifunctional adipokine linked with insulin resistance, obesity, and atherosclerotic disease, and a potential biomarker for infection inflammation, ischemia, or kidney injury." (PMID 39744637, 2024). "Furthermore, levels of LCN2 are elevated in cases of obesity and type 2 diabetes." (PMID 38673873, 2024). "Although LCN2 gene expression was increased in skeletal muscle of sarcopenic obese mice, whether it is a cause or a result of muscular atrophy in obesity due to inflammation and oxidative stress is not clear." (PMID 38035773, 2024). "LCN2 participated in obesity and its metabolic complications such as T2DM, and cardiovascular diseases, which may relate to the activation of LCN2 signaling (such as TNF-α/NLRP3/LCN2) inducing mitochondrial dysfunction, oxidative stress, insulin resistance, and macrophage activation in adipocytes." (PMID 39609876, 2024). "We speculated that OI led to reduced secretion of LCN2, which induce appetite increase and excess energy intake through regulating the activity of feeding center of hypothalamus, then leading to obesity, insulin resistance, hyperglycemia, hyperlipidemia, and muscle dysfunction." (PMID 37326909, 2024). "Furthermore, obesity and its consequences can lead to an imbalanced adipokine profile, increasing levels of proinflammatory adipokines and cytokines including retinol-binding protein 4, lipocalin 2, Leptin, and chemerin." (PMID 38898498, 2024). "Findings also support a positive association of serum lipocalin-2 with other cardiovascular disease risk factors such as abnormal lipids profile or increased fasting glucose and insulin levels, after 12-week supervised HIIT intervention among young men with obesity." (PMID 37238398, 2023). "LCN2 modulates expression of genes involved in β-oxidation in adipocytes, promotes β-cell function, and counteracts obesity-induced glucose intolerance suggesting LCN2 as an endogenous compensatory signal to counteract metabolic dysregulation in obesity through its anorexigenic activity." (PMID 37638032, 2023). "Moreover, lipocalin-2 is related to the buildout of obesity-related metabolic diseases." (PMID 37238398, 2023). "Indeed, some researchers have concluded that elevated LCN2 levels are linked to the obesity associated with PCOS, not to PCOS alone." (PMID 35206286, 2022). "However, genetic LCN2 deficiency does not accelerate diet-induced obesity, nor does it alter impaired glucose homeostasis or hepatic function." (PMID 36009315, 2022). "However, the relationship between LCN2 and the remission of obesity after bariatric surgery remain unclear." (PMID 35138515, 2022). "Consistently, increased LCN2 expressions have also been described in the brain regions in both ob/ob mice and mice fed high-fat diets, the two classical models with metabolic disorders characterized by obesity, hyperglycemia, dyslipidemia, systemic inflammation, and neuroinflammation." (PMID 34636748, 2021). "Changes in the production of adipokines such as leptin, resistin, lipocalin 2, tumor necrosis factor-α, chemerin, retinol binding protein 4, and interleukin-6 have been reported in obese individuals, and this can lead to the development of obesity-related metabolic diseases." (PMID 33498329, 2021). "On the other hand, it has recently been argued that rather than being causal of metabolic dysfunction, elevated Lcn2 may instead provide a protective mechanism to mitigate obesity-induced dysregulation and preserve pancreatic β-cell function." (PMID 33528828, 2021). "Interestingly, diabetes and obesity are also associated with increased susceptibility to severe influenza infection, but the potential correlation between LCN2 levels and disease outcome in humans is not known." (PMID 33905460, 2021).